SIRT1 (sirtuin 1)
Diseases named in the same sentence as SIRT1 in open-access papers (continued):
Sharing a sentence is not in itself a finding about the gene and the disease.
breast cancer (continued). "In breast cancer, SIRT1 modulation by RSV (10–50 μM) paradoxically exhibits dual roles: while SIRT1 overexpression promotes Akt activation, RSV-induced SIRT1 activation at physiologically relevant concentrations (e.g., 25 μM) enhances mitochondrial integrity and apoptosis." (PMID 40690143, 2025). "For instance, SIRT1 was observed to deacetylate FOXO3a to alter its activity to favor cell survival under chemotherapy, resulting in chemoresistance and reduced apoptosis in breast cancer cells." (PMID 41300302, 2025). "Among the sirtuins, SIRT1 and SIRT6 have been identified in EVs associated with breast cancer." (PMID 40214422, 2025). "Notably, SIRT1 is overexpressed in ER+ breast cancer cases and regulates TGF-β, suggesting a role in tumor progression." (PMID 41300302, 2025). "Additionally, exosomal miR-155-5p from MDSCs was shown to downregulate SIRT1 expression in breast cancer cells, thereby promoting epithelial-mesenchymal transition." (PMID 41281644, 2025). "Collectively, our results indicate that MDSC-derived miR-155-5p drives HR + breast cancer progression by suppressing SIRT1, and our engineered TME-responsive polymeric micelle system effectively addresses key pharmacological barriers to synergistic cancer treatment." (PMID 41281644, 2025). "In HR+ breast cancers, SIRT1 is often overexpressed and plays a pivotal role in tumor progression." (PMID 41300302, 2025). "Studies have shown that SIRT1 is upregulated in tamoxifen-resistant breast cancer cells." (PMID 41300302, 2025). "However, in some conditions, high SIRT1 boosts survival of metastatic breast cancer cells by suppressing NF-κB activity and oxidative stress." (PMID 41300302, 2025). "Furthermore, miR-155-5p downregulates SIRT1 expression, thereby advancing breast cancer epithelial-mesenchymal transition." (PMID 41281644, 2025). "Furthermore, HeLa cells derived from cervical cancer and MCF7 cells derived from breast cancer showed significant evidence of SIRT1 ISGylation upon doxorubicin treatment, suggesting that SIRT1 is a bona fide target for ISGylation in a subset of cancer cells." (PMID 38443596, 2024). "SIRT4 might affect breast cancer CSCs by altering SIRT1 expression, targeting H4K16Ac and BRCA1, and affecting the process of autophagy." (PMID 38397988, 2024). "This lncRNA, also called lncRNA-PRLB (progression-associated lncRNA in breast cancer), is upregulated in human breast cancer tissues and breast cancer cell lines Moreover, it has been described as a modulator of the SIRT1 gene both at the mRNA level and protein level." (PMID 38611028, 2024). "Moreover, in breast cancer cells, SIRT1 and FOXO4 collaborate to prevent cell apoptosis and promote tumor cell survival." (PMID 39845948, 2024). "SIRT1 is involved in many cellular processes including DNA repair and protects against radiation-induced apoptosis in different diseases such as brain, lung and breast cancers." (PMID 38909090, 2024). "Furthermore, SIRT1 was found to interact with Akt directly, consequently promoting the activity of Akt in breast cancer cells in vitro and positively correlating with expression of Akt, P-Akt, in breast cancer tissues in vivo." (PMID 37538932, 2023).
breast cancer (continued). "Thus, SIRT1 carries the survival signal from the estradiol in mammary tumor cells in a GPCR-dependent mechanism, which is different than those controlled by ERα or ERβ." (PMID 37762053, 2023). "Our results suggest that SIRT1 may play a tumor0protecting role in canine mammary tumors, as deductible from the shifts in subcellular localization." (PMID 37627400, 2023). "SIRT1 expression and function has been studied in human breast cancer and several other tumors in humans, in murine models, and in cultured tumor cells; however, it has hitherto neither been investigated in canine mammary tumors nor in normal mammary gland tissues." (PMID 37627400, 2023). "In addition, we examined the expression and subcellular localization of SIRT1 in cultured canine mammary cancer cells by Western blot and immunofluorescence analyses." (PMID 37627400, 2023). "SIRT1 expression was also discovered to be decreased in MNU-induced mammary tumors." (PMID 37388281, 2023). "In addition, it has been shown that the activation of miR-34a can induce apoptosis and/or senescence in breast cancer cells via the downregulation of Bcl-2 and SIRT1." (PMID 37833921, 2023). "This deregulation of SIRT1, observed in canine mammary tumors, might suggest a tumor-modulating role of this regulatory protein, exhibiting in its normal state a possible tumor-protecting function." (PMID 37627400, 2023). "SIRT1 controls lysosomal acidification to regulate breast cancer invasion." (PMID 37583461, 2023). "The roles of SIRT1 in breast cancer is multifaceted depending on its substrate from upstream or downstream signaling pathway, overexpression of SIRT1 significantly promoted breast cancer growth both in vitro and in vivo, whereas knockdown of SIRT1 inhibited these phenotypes." (PMID 37538932, 2023). "The expression of Bcl-2, an anti-apoptotic or pro-survival protein, was markedly decreased in MCF-7 and MDA-MB-231 breast cancer cells following the inhibition of SIRT1 with sirtinol, which indicates that SIRT1 promotes the growth of breast cancer through the upregulation of the Bcl-2 protein." (PMID 36291902, 2022). "miR-34a, a direct regulator of SIRT1, is decreased in breast cancer." (PMID 35087589, 2022). "Moreover, there is evidence that resveratrol induces toxicity in breast cancer cells through a SIRT1-dependent mechanism." (PMID 36291902, 2022). "Furthermore, NMNAT-1 has been shown to interact with SIRT1 in MCF-7 breast cancer cells and was recruited to target gene promoters by SIRT1 to support its deacetylase activity and transcriptional regulation." (PMID 35595095, 2022). "Furthermore, the downregulation of miR-34a in breast cancer is related to elevated expression of Bcl-2 and sirtuin-1 (Sirt1), and consequently the restoration of miR-34a expression leads to increased apoptosis rates." (PMID 35309939, 2022). "Moreover, a previous study showed that adiponectin enhances the expression of SIRT-1 via induction of reactive oxygen species (ROS) generation, raising a possibility of the implication of SIRT-1 in the anti-breast cancer effects of adiponectin." (PMID 34986886, 2022). "In addition, we provide the first evidence that SIRT-1 induction mediates metabolic actions and breast cancer cell death by adiponectin." (PMID 34986886, 2022). "Furthermore, a study demonstrated that miR-22 is downregulated in MCF-7 and MDA-MB-231 breast cancer cells, and the overexpression of miR-22 or SIRT1 knockdown induces apoptosis and decreases the survival of breast cancer cells." (PMID 36291902, 2022).
breast cancer (continued). "Being elevated in breast cancer, SIRT1 plays a significant role in this disorder." (PMID 35087589, 2022). "Recent studies have revealed that SIRT1 is constitutively upregulated in breast cancer cells." (PMID 36291902, 2022). "Additionally, SIRT1 has been shown to modulate different targets in breast cancer, including transcription factors, signaling molecules, and certain enzymes, showing opposing effects by its exhibition of either tumor promotion or tumor suppression." (PMID 36291902, 2022). "Taken together, these findings suggest that the interaction between SIRT1 and FoxO1 may play a role in the metastasis process and the treatment of breast cancer." (PMID 36142156, 2022). "So far, the information provided above reveals that most miRNAs targeting SIRT1 act as tumor suppressors in breast cancer; however, studies are needed to clarify and verify the possible tumor-promoting effects of SIRT1 negative regulation by miRNAs in breast cancer." (PMID 36291902, 2022). "Interestingly, SIRT1 has also been demonstrated to regulate the expression of certain catalytic proteins in breast cancer." (PMID 36291902, 2022). "Our findings of SIRT2 expression due to radioactivity in breast cancer was compared with SIRT1 expression showed that SIRT2 may clearly play an important role in breast cancer." (PMID 33705642, 2021). "While miR-22 expression was downregulated in breast cancer cells after IR, Sirt1 was upregulated." (PMID 34804940, 2021). "However, they found that overexpression of miR-22 regulated Sirt1 expression negatively, blocking its function, such as suppressing tumorigenesis and enhancing the radiosensitivity of breast cancer." (PMID 34804940, 2021). "Knockdown of SIRT1 in HMLER breast cancer cells increased metastasis." (PMID 34650436, 2021). "SIRT1 rs3758391 has been investigated in diffuse large B cell lymphoma, bladder, and breast cancer." (PMID 34942940, 2021). "Furthermore, in the basal-like and HER2-enriched breast cancer subtypes, SIRT1 seems to have a lower H-score than in the luminal molecular subtypes." (PMID 34663249, 2021). "Therefore, the combination of LUT and I3C exclusively suppresses ER+ breast cancer synergistically via regulating the SIRT1/ERα pathway." (PMID 33925607, 2021). "Sirt1 is a histone deacetylase that acts as a regulator in multiple physiological processes such as cell growth, apoptosis, DNA damage and, tumor development; in addition, it promotes tumorigenesis and is upregulated in breast cancer." (PMID 34804940, 2021). "Our previous study has found that Brachyury in breast cancer cells can act on SIRT1 to promote tamoxifen resistance, indicating that Brachyury may be a therapeutic target for breast cancer." (PMID 33734319, 2021). "The inflammatory cytokines/chemokines secreted by the adipose tissues in the local and/or system could activate the NF-kB, STAT3, HIF-1 and SIRT1 signaling pathways to promote invasion and metastasis of breast cancer." (PMID 34413268, 2021). "Even so, SIRT1 is regulated differently in the scope of tumors involving breast carcinoma." (PMID 33705642, 2021). "SincemiR22 has suppressive effects on breast cancer cells viatargeting SIRT1, miR22/SIRT1 axis may be used as anovel and potential therapeutic target for breast cancertreatment." (PMID 31606975, 2020). "Furthermore, SIRT1 (Sirtuin1) expression levels aresignificantly up-regulated in breast cancer tissues." (PMID 31606975, 2020). "Nevertheless, Sirt1 can still act as a tumor suppressor in breast cancer cells as well." (PMID 32426286, 2020).
breast cancer (continued). "Silent information regulator 2-related enzyme 1 (SIRT1) is a deacetylase dependent on nicotinamide adenine dinucleotide, which is highly expressed in a variety of tumors and has been proven to inhibit the growth of breast cancer cells." (PMID 33362547, 2020). "In breast cancer cells, SIRT1 depletion induced an epithelial shift and inhibited cell invasion." (PMID 33613454, 2020). "The activation of beta-adrenergic system has been associated with a upregulation of the expression of specific oncogenic signaling pathways including Sirtuin-1(Sirt-1) in cervical cancer, Src in ovarian cancer and Human Epidermal Growth Factor Receptor2 (Her2) in breast cancer." (PMID 33457324, 2020). "However, researchers also reported contradictory SIRT1 role as ERα repressor especially in breast cancer." (PMID 33330467, 2020). "Similarly, the inhibition of OGT expression and activity in breast cancer cell lines increased SIRT1." (PMID 31717261, 2019). "Further studies may clarify whether in breast cancer cells the SIRT1 inhibitory pathway contributes to this delayed apoptosis and the role of context specificities." (PMID 31726691, 2019). "Recently, H4 lysine 4 (H4K4ac) was identified as a new target of SIRT1 in breast cancer." (PMID 31261609, 2019). "Similarly, in breast cancer tissues and cells, SIRT1 is correlated with histological grade, tumor size, and lymph node metastasis." (PMID 31817470, 2019). "Either inhibition of SIRT1 by EX527 or knockdown of SIRT1 by siRNA could reverse NNMT-mediated resistance to adriamycin and paclitaxel, which suggests that SIRT1 plays a critical role in NNMT-related chemoresistance in breast cancer." (PMID 31101119, 2019). "A recent study reported that the inhibition of OGT expression and activity in breast cancer cell lines could induce SIRT1 stability." (PMID 31717261, 2019). "Given our previous findings demonstrating that DVL-1 plays a critical role in regulating a TIAM1-Rac1 signaling axis in MDA-MB-231 cells, and endogenous DVL-3 co-precipitates with SIRT1 in breast cancer cells, we were interested in exploring these two family members in particular." (PMID 30479694, 2018). "Afterward, we proceeded to examine whether there is an actual direct interaction between HDAC SIRT1 and histone H3 epi-marks in breast cancer." (PMID 30093977, 2018). "In conclusion, SIRT1 siRNA-mediated knockdown has significantly increased the acetylation levels of H3k4ac and H3k9ac at the breast cancer-related gene panel promoters; thus, SIRT1 mediates the deacetylation of histone marks H3k4ac, as well as H3k9ac, in breast cancer." (PMID 30093977, 2018). "This study reported that SIRT1 overexpression was associated with a worse OS in liver and lung cancers, while it was not correlated with OS in breast cancer, colorectal cancer, or gastric carcinoma." (PMID 30319549, 2018). "In addition, miR-22 overexpression suppresses tumorigenesis and improves radiosensitivity of breast cancer cells by targeting SIRT1 in vitro." (PMID 30380732, 2018). "In addition, the pro-survival effect of 17β-estradiol on breast cancer cells through GPER involves expression of SIRT1, a putative tumor suppressor, being a coactivator of FOXO3a." (PMID 30687231, 2018). "Similarly, knocking down Sirt1 in a murine triple-negative basal-like breast cancer cell line 4T1 significantly promoted mammosphere-formation." (PMID 30038266, 2018). "The authors concluded that SIRT1 is required for estrogen-induced breast cancer growth." (PMID 30380732, 2018).
breast cancer (continued). "We showed that SIRT1 modulates the acetylation patterns of histones H3 and H4 in breast cancer." (PMID 30093977, 2018). "Moreover, silencing SIRT1 induces epithelial-like ALDH1+ CSCs in BT549 breast cancer cells, which are basal-like and originally enriched with mesenchymal traits." (PMID 30038266, 2018). "Here, we demonstrated that SIRT1 knockdown could inhibit proliferation, metastasis, and chemoresistance in breast cancer cells, which was modulated by lncRNA-PRLB/miR-4766-5p network." (PMID 29752439, 2018). "The co-immunoprecipitation assays highlighted a global physical interaction between SIRT1 and H3k4ac as well as H3k9ac across all molecular subtypes, implying that SIRT1 could directly deacetylate H3k4ac and H3k9ac in breast cancer." (PMID 30093977, 2018). "Furthermore, the protein levels of SIRT1 protein and RNA in breast cancer cells were reduced by miR-4766-5p overexpression." (PMID 29752439, 2018). "Therefore, SIRT1 seems to exert tumor-suppressive properties in apocrine breast cancer as well, through epigenetic repression of the AR oncogene." (PMID 30093977, 2018). "SIRT1 also modulates histones H3 and H4 acetylated marks in different subtypes of breast cancer." (PMID 30093977, 2018). "Interestingly, 2 distinct patterns of H3k4ac and H3k9ac enrichment can be observed following SIRT1 knockdown, the patterns seem to be predominantly dependent on breast cancer cell line intrinsic subtype." (PMID 30093977, 2018). "It would be worthwhile to investigate whether PI3K/IGF-1R signaling is affected in human breast cancers in future study, especially those showing increased cytoplasmic but reduced nuclear level of SIRT1." (PMID 30038266, 2018). "SIRT1 is also involved in breast cancer progression and metastasis." (PMID 30380732, 2018). "However, despite the accumulated studies over the past decade, the role of SIRT1 in human breast cancer remains a subject of debate and controversy." (PMID 30380732, 2018). "In breast cancer, SIRT1-dependent epigenetic silencing of both oncogenes and TSGs is reported." (PMID 30380732, 2018). "We were interested in determining whether SIRT1 depletion could alter the relative expression patterns of H3k4ac, as well as H3k9ac and H4k16ac in breast cancer." (PMID 30093977, 2018). "Collectively, these data strongly support the hypothesis that lncRNA-PRLB promotes breast cancer cell proliferation and chemoresistance via miR-4766-5p-mediated regulation of SIRT1 signaling." (PMID 29752439, 2018). "Taken together, these results suggest that SIRT1 plays a bivalent subtype-dependent role in breast carcinoma, and that SIRT1 could also be a potential prognostic marker in breast cancer." (PMID 29340027, 2017). "Additionally, Sirt1 expression is increased in ovarian cancer and gastric cancer, whereas it is reduced in liver cancer and breast cancer." (PMID 29029516, 2017). "In addition to antiproliferative potency against leukemia and breast cancer cell lines, the SIRT1/2 inhibitor salermide reduces viability in spheroidal cultures of colorectal CSC cell lines." (PMID 28994177, 2017). "Our data also point to a potential role for SIRT1 as a prognostic biomarker in breast cancer." (PMID 29340027, 2017). "We also found an inverse correlation between SIRT1 expression and breast cancer aggressivity." (PMID 29340027, 2017). "Although some studies have investigated SIRT1 expression in breast cancer, however, this is the first study to extensively examine SIRT1 mRNA and protein expression levels according to intrinsic subtypes with a sample size that satisfies statistical power requirements." (PMID 29340027, 2017). "Previously, we found that miR-34a could inhibit the proliferation and migration of breast cancer by targeting B-cell lymphoma 2 (Bcl-2), silent information regulator 1 (SIRT1), E2F transcription factor 3 (E2F3) and CD44." (PMID 29037220, 2017).